FKBP5 (FKBP prolyl isomerase 5)
Diseases named in the same sentence as FKBP5 in open-access papers (continued):
Sharing a sentence is not in itself a finding about the gene and the disease.
mental disorder (19 papers, 2014 to 2025). A disease that has its basis in the disruption of mental process. "FK506-binding protein 51 (FKBP51 or FKBP5) serves as a crucial stress modulator implicated in mental disorders, presenting a potential target for intervention." (PMID 40096182, 2025). "Genome-wide association studies (GWAS) focusing on single nucleotide polymorphisms (SNPs) have uncovered noteworthy associations between allelic variants of the FKBP5 gene and mental disorders." (PMID 38786025, 2024). "Polymorphisms in FKBP5 (rs1360780) can increase the risk of stress-related mental disorders in adulthood due to the methylation of the FKBP5 gene locus occurring as a consequence of childhood-dependent traumatic stress." (PMID 32932645, 2020). "The authors suggest that, in essence, FKBP5 could represent a broader stress-modulating element that contributes to both increased susceptibility and resilience across various mental disorders by mitigating the detrimental impacts of adverse life events." (PMID 39272997, 2024). "A wealth of data from genetic, epigenetic, and postmortem data support the fact that increased FKBP5 expression is associated with the risk of mental disorders, and the manipulation of FKBP5 in preclinical studies leads to the normalization of impaired behavior." (PMID 37581323, 2024). "We would encourage the examination of this gene in appropriate studies that characterize the effects of these more extreme exposures and conditions to provide additional insight on the role of placental FKBP5 in behavioral and mental disorder risk with more extreme stressors." (PMID 25115650, 2014). "FKBP5 has been of special scientific interest in the behavioral sciences since it has been involved in the pathophysiology of several mental disorders." (PMID 40149476, 2025). "During the last 15 years, FKBP5 has been of special scientific interest in the behavioral sciences since it has been involved in the pathophysiology of several mental disorders." (PMID 40149476, 2025). "FKBP5 gene plays a vital role in the stress response system, and childhood maltreatment as an environmental stressor may be more likely to cause alterations in FKBP5 gene methylation, and the alteration in DNA methylation of the FKBP5 gene has been shown to be a risk factor for mental disorders." (PMID 35185646, 2022). "Nonetheless, some of the DEGs—that had the same direction of expression change both in the mouse model of SDS and human postmortem PFC samples—are genes known to be connected with the development of mental disorders: Fkbp5, Il1r, Lpr8, and Txnip." (PMID 36430271, 2022). "There is also some evidence of interactions between early trauma and FKBP Prolyl Isomerase 5 (FKBP5) in mental disorders generally." (PMID 34262598, 2021). "Altered methylation of the FKBP5 gene has been observed in various mental disorders and attributed to the effects of adverse childhood experiences (ACEs)." (PMID 33255215, 2020). "Therefore, current evidence supports that FKBP5 plays a cross-cutting role in multiple mental disorders." (PMID 40149476, 2025). "This makes FKBP5 a potential target for stress-related mental disorders." (PMID 40096182, 2025). "FKBP5, representing a molecular hub modulating many cellular pathways, is a novel and very promising candidate to target component of the stress hormone system and to ameliorate stress-related mental disorders and other sequelae of stress." (PMID 30890970, 2019). "FKBP5, respectively, FK506 binding protein 51/FKBP51 regulates the responsiveness of the GR and the HPA axis and is also implicated in important gene x environment interactions underlying stress-related mental disorders, making it a promising drug target." (PMID 30890970, 2019). "FKBP5 antagonists may be promising new treatment options for patients suffering from stress-related mental disorders and who have an altered functioning of FKBP5/GR/HPA axis signaling." (PMID 30890970, 2019).
mental disorder (continued). "This study aims to identify potential ligands that can effectively interact with FKBP5 protein, modulate its activity, and serve as either molecular markers for research studies or offer therapeutic advantages to individuals with stress-related mental disorders in the long run." (PMID 40096182, 2025). "Therefore, because of its central and systemic roles and its specific pattern of gene–environment interactions, FKBP5 is a good model to understand the complex relationship between environmental exposures and genetic variation in the origin of mental disorders." (PMID 40149476, 2025). "The research progress of NR3C1, FKBP5, BDNF, KITLG and other genes will provide a solid theoretical basis for the improvement of mental disorders in children after trauma." (PMID 36458128, 2022). "Early-life stress may also impact methylation of other genes related to the pathophysiology of various mental disorders, such as BDNF, COMT, MAOA, FKBP5, and SLC6A4." (PMID 33284958, 2021). "Moreover, other known risk indicators that might become available within days of traumatic exposure (e.g., childhood trauma, lifetime mental disorders, ED stress hormones, gene variants (e.g., FKBP5), or ED gene expression profiles) have not been assessed in this study." (PMID 25886446, 2015).
psychosis (14 papers, 2006 to 2025). "Common variations of the FKBP5 gene have been reported to impact the risk of psychosis by moderating the effects of environmental exposures." (PMID 35329940, 2022). "The role of various FKBP5 gene variants can be beneficial or detrimental when considering the risk of illness, worsening of psychosis, and response to therapy." (PMID 35223250, 2022). "Our results suggest that there is an association between variants of the FKBP5, lifetime traumatic events and risk of psychosis." (PMID 33925151, 2021). "Results of this study support previous findings from studies testing the moderating effects of the FKBP5 gene polymorphisms on the association between trauma exposure and a risk of psychosis or PLEs." (PMID 33925151, 2021). "Common variations of the FKBP5 gene are implicated in psychotic disorders, by modulating the hypothalamic–pituitary–adrenal axis reactivity to stress." (PMID 33925151, 2021). "The FKBP5 polymorphisms have been shown to be associated with psychosis after the inclusion of ACEs as the confounding factor." (PMID 33255215, 2020). "Lower levels of FKBP5 methylation were associated with better cognitive performance and higher functional capacity in patients with psychosis." (PMID 33255215, 2020). "Authors reported a significant effect of the interaction between the FKBP5 rs1360780 polymorphism and parental separation on psychosis risk." (PMID 28822116, 2018). "This work expands on previous GxE research supporting that the interaction between FKBP5 variability and childhood adversity exposure increases the risk for psychosis phenotypes." (PMID 27389186, 2016). "The outcomes of interest were the logistic regression statistics, which assess the association between FKBP5 and psychotic disorder." (PMID 25101008, 2014). "With this in mind, we set out to test the credentials of FKBP5 (FK506 binding protein 5) as a genetic risk factor for psychosis." (PMID 25101008, 2014). "For its part, an investigation with a Belgian sample of healthy children of people with psychotic disorders and patients with psychotic disorders demonstrated that the FKBP5 polymorphisms that had a significant interaction with child abuse on psychosis were the A-alleles of rs4713916 and rs9296158." (PMID 40149476, 2025). "Further research should investigate both non-clinical and clinical samples to identify whether the moderating effect of variants in the FKBP5 gene on presented associations is relevant for the whole psychosis continuum." (PMID 35329940, 2022). "The FKBP5 gene contains several polymorphic sites that may affect stress response, and thus a risk of psychosis." (PMID 33925151, 2021). "The gene by which ACEs interactions that might impact a risk of various neuropsychiatric disorders, including psychosis, has been described as the FKBP5 gene." (PMID 33255215, 2020). "Our findings suggest that hypomethylation of the FKBP5 appears at early stages of psychosis and might be associated with a history of ACEs as well as less severe clinical manifestation." (PMID 33255215, 2020). "Stratification of association between FKBP5 and psychotic disorder by parental separation." (PMID 25101008, 2014). "This study attempted to investigate whether the etiological heterogeneity typically found in large clinical cohorts is a root cause of the uncertainty regarding FKBP5’s relevance to psychosis." (PMID 25101008, 2014). "Main effects of environmental risk factors and FKBP5 on psychotic disorder." (PMID 25101008, 2014). "Moreover, the association between exposure to ACEs and the level of FKBP5 methylation in patients with psychotic disorders remains unknown." (PMID 33255215, 2020). "Therefore, taken together, findings are in line with the notion that the contribution of FKBP5 variability to psychosis risk may be dependent upon the presence of specific environmental exposures." (PMID 27389186, 2016).
psychosis (continued). "There is post-mortem evidence of increased FKBP5 expression in cortical and hippocampal regions of people with mood and psychotic disorders." (PMID 40149476, 2025). "FKBP5 gene plays a role in the evolution of psychosis and the progression of SCZ in response to chronic and acute stress and alteration of brain regions related to stress hormones." (PMID 35223250, 2022). "Therefore, considering that the FKBP5 gene has been implicated in the development and severity of psychosis and PLEs, it may suggest that anxious attachment style is associated with different neurobiological mechanisms compared to other insecure attachment styles i.e., avoidant attachment." (PMID 35329940, 2022). "So far, studies investigating interactions of the FKBP5 gene with stress exposure in individuals with psychosis and PLEs have mostly focused on childhood trauma experience." (PMID 33925151, 2021). "It has been shown that patients with psychosis present increased expression of FKBP5 mRNA in the dorsolateral prefrontal cortex and the hippocampus when compared to healthy controls." (PMID 33925151, 2021). "The present study indicates that variation in the FKBP5 gene also moderates the effects of lifetime traumatic events on psychosis proneness." (PMID 33925151, 2021). "The present study provides the first evidence of the interplay between childhood bullying and FKBP5 variability in the real-world expression of psychosis proneness and social stress reactivity." (PMID 27389186, 2016). "To date, interactions between potential molecular genetic susceptibility and exposure to childhood adversity in predicting development of psychosis have mainly focused on candidate genes such as FKBP5, BDNF, and COMT." (PMID 27648571, 2016). "FKBP5, synonymous to FKBP51 and FKBP54, is located on chromosome 6p21, a chromosomal region associated with bipolar disorder and psychosis and consists of 10 exons spanning ~156 kb (UCSC Genome Browser, release August 2004)." (PMID 17081296, 2006). "Notably, the FKBP5 gene functions in developing psychosis and the outcome of SCZ amidst exposure to acute or chronic stress." (PMID 35223250, 2022). "It has been reported that specific SNPs of the FKBP5 gene may have an impact on the severity of psychotic symptoms in patients with psychosis after adjustment for exposure to TLEs." (PMID 33925151, 2021). "The present study indicates that variation in the FKBP5 gene might moderate the effects of lifetime traumatic events on psychosis proneness." (PMID 33925151, 2021). "Moreover, ACEs have been demonstrated to interact with variation in the FKBP5 gene affecting clinical manifestation of psychosis and cognitive performance." (PMID 33255215, 2020). "Altogether these findings suggest that hypomethylation of the FKBP5 in early psychosis might be a protective mechanism against elevated cortisol levels." (PMID 33255215, 2020). "In conclusion, results of this study indicate that decreased methylation of the FKBP5 gene might be observed in patients at early stages of psychotic disorder." (PMID 33255215, 2020). "Therefore, in this study we aimed to determine the FKBP5 methylation in patients with psychosis and controls, taking into account the effects of ACEs." (PMID 33255215, 2020). "Future studies should investigate at-risk and clinical samples to identify whether the interaction between bullying and FKBP5 variability is relevant across the psychosis continuum." (PMID 27389186, 2016). "Of note, neither our study nor previous ones in nonclinical and clinical samples found that FKBP5 variability by itself was associated with positive psychotic phenomena or presence of a psychotic disorder." (PMID 27389186, 2016). "We investigated whether FKBP5 and BDNF genotype moderated the association between CT and two proxies of hippocampal integrity differently in individuals with a diagnosis of a psychotic disorder, compared to healthy siblings." (PMID 24658422, 2014).
psychosis (continued). "Effect of FKBP5 on psychosis caseness after adjusting for environmental exposures." (PMID 25101008, 2014). "The present study investigated whether synergistic effects of CT and BDNF/FKBP5 genotype influenced two proxies of hippocampal integrity in a large sample of individuals with psychotic disorder and siblings." (PMID 24658422, 2014). "Two studies have already looked at the possible relevance of FKBP5 to psychosis." (PMID 25101008, 2014). "Although, we were able to detect the hypothesized effect of FKBP5 on presence of psychotic disorder, the fact that our ability to detect this signal depended on controlling for environmental exposures suggests that FKBP5’s contribution may vary depending on the etiology relevant to each case." (PMID 25101008, 2014). "There are also studies addressing the effects of interaction between variability in the FKBP5 gene and childhood trauma on psychosis phenotypes in clinical and non-clinical populations." (PMID 28822116, 2018). "No main effect between FKBP5 and psychotic disorder was observed in either crude or adjusted models." (PMID 25101008, 2014). "So far, the effect of BDNF/FKBP5 by CT interactions on hippocampal volume in the context of psychosis has not been investigated." (PMID 24658422, 2014). "These FKBP5 genotype by trauma interactions were also found in different follow-up samples at different levels of psychosis severity and familial liability, although not always consistently so." (PMID 24658422, 2014). "However, the level of FKBP5 methylation has not been investigated in patients with psychotic disorders." (PMID 33255215, 2020).
asthma (13 papers, 2013 to 2025). "The protein is encoded by the FKBP5 gene, which was shown to have increased expression in those with severe asthma in the U-BIOPRED cohort." (PMID 34721414, 2021). "The two CpGs recognized as eQTMs for FKBP5 map to regulatory features, and there is interaction between the two regulatory features possibly accounting for the correlation observed between the two CpGs and asthma risk." (PMID 38806494, 2024). "Interestingly, a small subpopulation of mast cells comprised mostly of cells from asthma horses and displayed higher expression of e.g., the asthma associated genes FKBP5, RGS1 and LTC4S, suggesting a role in inflammation." (PMID 37758813, 2023). "Here, we identified FKBP5 in the 15 most differentially expressed genes for asthma and also show epigenetic variation at two interacting regulatory regions possibly accounting for the differential expression." (PMID 38806494, 2024). "Overall, the expression of FKBP5 was higher in the asthma cases in all other sites, except for those recruited in Denver." (PMID 38806494, 2024). "As such, further studies are needed to fully understand the role of FKBP5 in asthma, as well as in corticosteroid response in horses." (PMID 37758813, 2023). "The ROC curves illustrated that FKBP5, WNT5A, PDK4, and GMPR had potential diagnostic value for asthma." (PMID 36550577, 2022). "Among them, PDK4, FKBP5, ZBTB16, WNT5A, GMPR and WIF1 are reported to be associated with asthma in the previous researches." (PMID 36550577, 2022). "FKBP5 was also upregulated in severe asthma indicating exposure to steroids but was expressed to a lower extent in peripheral airways suggesting that treatment is not exerting the same biological effect in this lung region." (PMID 28045928, 2017). "Testing for differential DNAm by asthma status, we found only five of these CpGs to be DMCs (i.e. significant for asthma at the Bonferroni level of p < 0.05/915): two CpGs for FKBP5 (cg03546163, cg23416081), two for TREML2 (cg26928682, cg18297196) and one for TMEM71 (cg27159719)." (PMID 38806494, 2024). "The AUC value of FKBP5 (AUC = 0.832), WNT5A (AUC = 0.813), TM4SF1 (AUC = 0.769), PDK4 (AUC = 0.753), EPAS1 (AUC = 0.748) and GMPR (AUC = 0.705) was more than 0.7, which suggesting higher diagnostic value for asthma." (PMID 36550577, 2022). "FKBP5, WNT5A, TM4SF1, PDK4, EPAS1 and GMPR had potential diagnostic value for asthma." (PMID 36550577, 2022). "Additionally, FKBP5 was significantly upregulated in the central airways in severe asthma, indicative of a strong response to glucocorticosteroids at this large central airways site." (PMID 28045928, 2017). "While the number of statistically significant DE transcripts (n = 60) is not negligible, for the majority of these transcripts (80%) the expression difference between normal and asthma-at-risk DC does not exceed 1.5 fold, and only one transcript (Fkbp5) changes more than two-fold." (PMID 23950928, 2013). "The 15 most significant DEGs included genes known to play a role in wound healing (FN1, CDH11), immune response (VSIG4, HS3ST4), and asthma drug response (PTHHD4, SPTBN1, FKBP5)." (PMID 38806494, 2024). "Saygideger conducted a meta-analysis and revealed that childhood trauma induces asthma or other chronic inflammatory diseases by influencing genes such as NR3C1 and FKBP5, which mediate immune inflammation." (PMID 36458128, 2022). "Heterogeneity in the severe asthma samples was evaluated using the IL-13 disease signature (CLCA1, SERPINB2 and POSTN) and the gene expression marker for steroid response (FKBP5)." (PMID 28045928, 2017). "Whilst microarray analysis and RT-qPCR identified some expression of FKBP5 within the peripheral airways, this was much lower than the expression in the central airways in severe asthma and not significantly different from healthy controls." (PMID 28045928, 2017).